PRAMEF13 (PRAME family member 13)
Tractability: No criterion of Open Targets' tractability assessment is met for any kind of drug.
Gene: Protein-coding gene on chromosome 1 (13,196,188 to 13,201,409, reverse strand). Ensembl gene ENSG00000279169.
Gene Ontology:
Molecular function: ubiquitin-like ligase-substrate adaptor activity
Biological process: proteasome-mediated ubiquitin-dependent protein catabolic process; negative regulation of apoptotic process; negative regulation of cell differentiation; negative regulation of DNA-templated transcription; positive regulation of cell population proliferation
Cellular component: Cul2-RING ubiquitin ligase complex; cytoplasm
Homologues: Orthologues: mouse Pramel12 (44% identical), rat Pramef8 (44% identical), mouse Pramel13 (41% identical), mouse Pramel21 (41% identical), mouse Pramel11 (41% identical), mouse Pramel20 (41% identical), mouse Pramel24 (41% identical), mouse Gm13040 (40% identical), mouse Gm13043 (40% identical), mouse Gm13057 (40% identical), mouse Pramel16 (40% identical), mouse Pramel31 (40% identical), and 78 more. Paralogues in human: PRAMEF14 (97% identical), PRAMEF1 (97% identical), PRAMEF2 (93% identical), PRAMEF18 (61% identical), PRAMEF19 (61% identical), PRAMEF17 (59% identical), PRAMEF10 (59% identical), PRAMEF33 (59% identical), PRAMEF12 (53% identical), PRAMEF7 (52% identical), PRAMEF8 (52% identical), PRAMEF20 (50% identical), and 12 more.